H19 (H19 imprinted maternally expressed transcript)
Diseases named in the same sentence as H19 in open-access papers (continued):
Sharing a sentence is not in itself a finding about the gene and the disease.
Anxiety (3 papers, 2016 to 2022). Intense feelings of nervousness, tension, or panic often arise in response to interpersonal stresses. "However, in another study, maternal anxiety was associated with decreased IGF2/H19 ICR DNA methylation in cord blood of female neonates." (PMID 34572069, 2021). "While we observed lower DNA methylation in IGF2/H19-CpG1, 4, and 6 in boys exposed to higher levels of maternal anxiety in the third trimester, we observed higher DNA methylation in these locations for girls." (PMID 34572069, 2021). "There were no sex interactions in the third trimester on other CpGs of IGF2/H19, or on the effect of maternal anxiety in the first and second trimester on any of the CpG of IGF2/H19." (PMID 34572069, 2021). "We report strong and consistent evidence of an association between maternal anxiety and decreased IGF2/H19 ICR methylation at the major CpG sites across the region investigated and these associations persisted when accounting for a range of covariates." (PMID 27023171, 2016). "This study provides consistent evidence in a large, well-characterized population-based birth cohort of a prospective association between maternal anxiety during pregnancy and reduced infant IGF2/H19 ICR cord blood methylation." (PMID 27023171, 2016). "However, for girls, there was a positive association between maternal anxiety during the third trimester and the methylation level of IGF2/H19 CpGs, with higher maternal anxiety predicting higher methylation levels." (PMID 34572069, 2021). "Thus, we added evidence to the suggestion that maternal anxiety during pregnancy can influence IGF2/H19 in a sex-specific manner." (PMID 34572069, 2021). "In the current study, we assessed whether maternal mental health during pregnancy (depression, anxiety and perceived stress) was associated with cord blood methylation, focusing on the IGF2/H19 ICR, one of the key imprinted loci, and IGF2 DMR0." (PMID 27023171, 2016). "Further work is required to characterize the relationships between maternal anxiety, IGF2/H19 ICR methylation, birth outcomes and subsequent long-term offspring health." (PMID 27023171, 2016). "This study found a negative association between maternal anxiety and methylation levels in boys and a positive association in girls for IGF2/H19 ICR." (PMID 36430406, 2022). "For boys, there was a negative association between maternal anxiety during the third trimester and the methylation level of IGF2/H19 CpGs, with higher maternal anxiety predicting lower methylation levels." (PMID 34572069, 2021). "For IGF2/H19 ICR, we found a negative association between maternal anxiety and methylation levels in boys, in contrast to a positive association in girls." (PMID 34572069, 2021).
Barrett esophagus (3 papers, 2013 to 2017). Esophageal lesion lined with columnar metaplastic epithelium which is flat or villiform. "The lncRNA HNF1A-AS1 has been reported to interact with HNF1A and H19 to regulate oesophageal adenocarcinoma occurrence and progression." (PMID 29100339, 2017). "Yang and colleagues have provided evidence that the important cancer-related lncRNA H19 may represent a downstream effector of HNF1A-AS1 in esophageal adenocarcinoma." (PMID 25863539, 2015).
chronic myelomonocytic leukemia (3 papers, 2016 to 2018). A myelodysplastic/myeloproliferative neoplasm which is characterized by persistent monocytosis, absence of a Philadelphia chromosome and BCR/ABL fusion gene, fewer than 20 percent blasts in the bone marrow and blood, myelodysplasia, and absence of PDGFRA or PDGFRB rearrangement. "Reduced expression of H19 was observed in clinically untreated chronic myeloproliferative disorders, including chronic myeloid leukemia (CML), polycythemia vera (PV), essential thrombocythemia (ET), primary myelofibrosis (PMF) and chronic myelomonocytic leukemia (CMML), as well as in AML." (PMID 27177333, 2016).
chronic obstructive pulmonary disease (3 papers, 2016 to 2025). A chronic and progressive lung disorder characterized by the loss of elasticity of the bronchial tree and the air sacs, destruction of the air sacs wall, thickening of the bronchial wall, and mucous accumulation in the bronchial tree. "Increased expression of H19 and miR-675, as well as altered methylation of the H19 imprinting control region, are associated with a low fat-free mass index in patients with chronic obstructive pulmonary disease." (PMID 30154386, 2018).
diabetic kidney disease (3 papers, 2020 to 2025). Progressive kidney disorder caused by vascular damage to the glomerular capillaries, in patients with diabetes mellitus. "This study indicates that inhibition of LncRNA H19 represents a novel anti-fibrotic treatment for diabetic kidney diseases." (PMID 33324218, 2020).
Duchenne muscular dystrophy (3 papers, 2019 to 2024). Duchenne muscular dystrophy (DMD) is a neuromuscular disease characterized by rapidly progressive muscle weakness and wasting due to degeneration of skeletal, smooth and cardiac muscle. "In Duchenne Muscular Dystrophy (DMD), H19 interaction with dystrophin is impaired, resulting in the degradation of dystrophin and muscle degeneration." (PMID 39416175, 2024).
embryonal tumors (3 papers, 2013 to 2023). "It has been hypothesized for many years that a potential tumor suppressor gene is present at chromosome 11p15.5 where H19 is located, because a loss of heterozygosity at this locus is observed in certain embryonal tumors." (PMID 23711233, 2013). "The mosaicism for IC1 (H19 gene) hypermethylation and differences of has been observed in a subset of patients with BWS in a risk for embryonal tumors in early childhood." (PMID 37052241, 2023).
follicular thyroid carcinoma (3 papers, 2019 to 2022). "High lncRNA H19 expression was positively correlated with the growth, migration, and invasion of lung tumor cells, but low H19 expression is associated with poor prognosis for patients with microinvasive follicular thyroid carcinoma and can be used to predict distant metastasis." (PMID 36158885, 2022). "However, little was known as to whether there was an association between H19 and minimally invasive follicular thyroid carcinoma (MI-FTC)." (PMID 31791180, 2019). "Targeted inhibition of long non-coding RNA H19 blocks anaplastic thyroid carcinoma growth and metastasis and expression of long non-coding RNA H19 predicts distant metastasis in minimally invasive follicular thyroid carcinoma." (PMID 35139769, 2022).
Hepatitis (3 papers, 2020 to 2024). Inflammation of the liver. "Intriguingly, our studies showed that treatment with GW4869 significantly ameliorated ConA‐induced hepatitis and reduced H19 levels both in the liver and hepatocytes." (PMID 37398637, 2023). "Scheme depicting M1‐derived exosomes transfer of lncRNA H19 into hepatocytes and its role in the progression of conA‐induced hepatitis." (PMID 37398637, 2023). "The inhibition of exosomes with GW4869 alleviated ConA‐induced hepatitis and decreased the expression of H19." (PMID 37398637, 2023). "In conA‐induced hepatitis, the lncRNA H19 is primarily expressed in type I macrophage (M1)." (PMID 37398637, 2023). "Collectively, these results indicated that increased H19 exacerbated ConA‐induced hepatitis." (PMID 37398637, 2023). "However, the role of H19 in ConA‐induced hepatitis remains largely undefined." (PMID 37398637, 2023). "Herein, we aimed to investigate whether H19 and exosomes play a key role in ConA‐induced hepatitis." (PMID 37398637, 2023).
hypoxic-ischemic encephalopathy (3 papers, 2022 to 2025). "Another predicted interaction was between the lncRNA H19 and miR-130a-3p, which has been reported in neonatal hypoxic-ischemic encephalopathy, where H19 binds to miR-130a-3p in SH-SY5Y and N2a cells." (PMID 41163216, 2025).
kidney cancer (3 papers, 2016 to 2022). Primary or metastatic malignant neoplasm involving the kidney. "For example, KCQN1OT1 and MALAT-1 are the kidney cancer-associated onco-lncRNAs, and H19 and GAS5 are the kidney cancer-associated tumor suppressive lncRNAs." (PMID 34983363, 2022).
kidney tumor (3 papers, 2007 to 2022). "A tumor suppressor activity was postulated showing that H19 overexpression lowered the tumorigenic properties of cells derived from kidney tumor." (PMID 17786216, 2007). "Overexpression of H19 in kidney tumor cells reduced the growth rate along with the absence of neoplasm in mice, suggesting the tumor suppressor capacity of H19 in renal carcinogenesis." (PMID 36110523, 2022).
metastatic prostate carcinoma (3 papers, 2018 to 2019). A carcinoma that arises from the prostate gland and has spread to other anatomic sites. "For example, LncRNA H19 is down-regulated significantly in the cell line M12 of metastatic prostate carcinoma." (PMID 31572428, 2019). "The NMT1 targeting miR-675-5p, which is down regulated in metastatic prostate cancer, derives from the lncRNA H19." (PMID 29579063, 2018).
Myocardial fibrosis (3 papers, 2020 to 2022). "Immunofluorescence staining was conducted on myocardial fibrosis-associated marker collagen III and H19 significantly suppressed the expression of collagen III." (PMID 36044268, 2022). "H19 inhibition further enlarged the infract size, deteriorated the compromised cardiac function and aggravated the degree of myocardial fibrosis (P < .05)." (PMID 31755219, 2020). "Moreover, the measurement of myocardial fibrosis areas exposed that myocardial fibrosis was also decreased in DCM+H19 group compared with that in DCM group (P < 0.05)." (PMID 36044268, 2022). "However, every coin has two sides, and high expression of H19 can also promote the occurrence of myocardial fibrosis." (PMID 35637964, 2022). "In addition, miR‐22‐3p overexpression also partly offset the cardiac function improvement and myocardial fibrosis reduction induced by H19 (P < .05)." (PMID 31755219, 2020). "Therefore, enforced H19 expression resulted in smaller infract size, better cardiac performance and less myocardial fibrosis when compared with those in the control group." (PMID 31755219, 2020). "In addition, data also indicated that up‐regulated H19 could alleviate myocardial fibrosis as well as decrease the expression of pro‐fibrogenic mediators such as collagen I, collagen III and TGF‐β (P < .05)." (PMID 31755219, 2020). "This may be related to the direct interaction of H19 with YB-1 under hypoxia, and the inhibition of YB-1 can promote the expression of COL1A1 and lead to myocardial fibrosis." (PMID 35637964, 2022).
overgrowth syndrome (3 papers, 2013 to 2025). A group of syndromes caused by genetic birth defects that may lead to the development of malignancies. "From the study of overgrowth syndrome-associated WT, germline dysregulation was identified in the imprinted region at 11p15 affecting imprinted genes IGF2 and H19." (PMID 25478630, 2014). "This analysis showed that normal kidney clonal expansions occur not only in mosaic hypermethylation of H19, but also in late mosaic chromosome 11p LOH in children without any reported phenotype of overgrowth syndrome." (PMID 39665570, 2025).
periodontitis (3 papers, 2016 to 2024). An acute or chronic inflammatory process that affects the tissues that surround and support the teeth. "Similar pro-autophagic effects were observed for lncRNA H19 in periodontitis." (PMID 39716252, 2024).
pneumonia (3 papers, 2022 to 2023). An acute, acute and chronic, or chronic inflammation focally or diffusely affecting the lung parenchyma, caused by an infection in one or both of the lungs (by bacteria, viruses, fungi, or mycoplasma.). "Another study also showed that inhibiting the expression of H19 can alleviate inflammation by regulating miR-140-5p/TLR4 axis in pneumonia." (PMID 36188624, 2022). "Sun showed that H19 was significantly increased in LPS-induced pneumonia models and sponging of miR-22-3p positively regulated NLRP3 to promote cell pyroptosis." (PMID 36188624, 2022). "In conclusion, H19 plays a positive promoting role in the pneumonia model." (PMID 36188624, 2022). "Therefore, H19-targeted therapy may play a role in the treatment of pneumonia." (PMID 36188624, 2022). "Similarly, Yang provided evidence that H19 silencing alleviates LPS-induced apoptosis and inflammation by regulating the miR-140-5p/TLR4 axis in cell models of pneumonia." (PMID 37841928, 2023).
sarcoma (3 papers, 2010 to 2026). A usually aggressive malignant neoplasm of the soft tissue or bone. "This study evaluated the association between H19 expression and overall survival in sarcoma patients, indicating a potential prognostic role for H19 as a biomarker." (PMID 41521159, 2026). "In the group of sarcoma cell lines, the average expression level of H19 of all four subtypes was found to lie in the medium range compared to the included cancer types." (PMID 41521159, 2026). "In the third step, we analyzed the expression of H19 in 7 different sarcoma cell lines using RT‐qPCR." (PMID 41521159, 2026). "In the present study 18% of sarcomas were found positive for the long non-coding RNA H19 by Tissue-Micro-Array." (PMID 33322802, 2020). "The proportion of H19 positivity significantly differed between histological subgroups, varying from three out of 34 (9%) in sarcomas other than liposarcoma, leiomyosarcoma and synovial sarcoma, to seven of 17 (41%) in synovial sarcoma (p = 0.02)." (PMID 33322802, 2020). "Whether and to what extent the lncRNA H19 is expressed in the heterogeneous group of sarcomas is largely unknown." (PMID 41521159, 2026). "We analyzed H19 expression patterns in various cancer cell lines, focusing on sarcoma subtypes." (PMID 41521159, 2026). "Furthermore, the present study is the ideal framework to better explore the prognosis/predictive value of an emergent biomarker in sarcoma: H19." (PMID 33322802, 2020).
sarcopenia (3 papers, 2016 to 2025). Progressive decline in muscle mass due to aging which results in decreased functional capacity of muscles. "Future studies are needed to identify the exact relationship between sarcopenia and H19." (PMID 39764565, 2025). "Type II muscle fiber loss/atrophy is also an important contributing factor in the development of muscle weakness during aging, which suggests that patients with sarcopenia could also benefit from an H19-Rgof treatment." (PMID 34454586, 2021). "Taken together, these results indicate that H19 influences muscle regeneration, glucose, and lipids metabolisms, which might be potentially involved in the crosstalk between adipose tissue and muscle and is a potential biomarker for sarcopenia and cachexia." (PMID 39764565, 2025).
squamous cell carcinoma (3 papers, 2018 to 2021). A carcinoma arising from squamous epithelial cells. "The rs217727 SNP in lncRNA H19 was significantly associated with susceptibility to LC, particularly in squamous cell carcinoma and adenocarcinoma, and identified the homozygous A/A genotype as a risk factor for LC." (PMID 30071841, 2018).
synovial sarcoma (3 papers, 2009 to 2026). "The higher frequency of H19 in synovial sarcoma suggests its potential as a specific biomarker and potential therapeutic opportunity for this subtype." (PMID 41521159, 2026). "Loss of imprinting (LOI) concurrent to hypomethylation at the H19/IGF2 intergenic region has been observed in a limited number of primary synovial sarcomas and SYT-SSX expression has been shown to induce IGF2 in immortalized MRC5 fibroblasts and HEK 293 cells." (PMID 19936258, 2009). "H19 was detected in 18% (n = 134) of tumor tissue samples with varying expression levels among the different soft tissue sarcoma subtypes, with the highest proportion observed in synovial sarcoma tissue (41%; p = 0.02)." (PMID 41521159, 2026). "To investigate the relevance of H19 in soft tissue sarcoma as a potential therapeutic target, we established a gene knock‐down approach by using Gapmers directed against H19 in two independent soft tissue sarcoma cell lines (synovial sarcoma SW982 and liposarcoma SW872)." (PMID 41521159, 2026).
teratoma (3 papers, 2013 to 2021). A non-seminomatous germ cell tumor characterized by the presence of various tissues which correspond to the different germinal layers (endoderm, mesoderm, and ectoderm). "Benign ovarian teratomas show a varying degree of H19 hypomethylation, and DNA prepared from cultured teratoma cells shows extreme hypomethylation of the H19 locus." (PMID 34680193, 2021). "It has been proposed that the up-regulation of H19 in VSELs might be involved in the maintenance of the quiescent stage and prevention of teratoma formation in adult tissues." (PMID 23570331, 2013). "In contrast, with the exception of H19 CTCF6, the majority of extragonadal teratomas in both males and females had methylation levels in the normal range for an imprinted locus (33-66%)." (PMID 23806198, 2013).
3-M syndrome (2 papers, 2013 to 2014). 3M syndrome is a primordial growth disorder characterized by low birth weight, reduced birth length, severe postnatal growth restriction, a spectrum of minor anomalies (including facial dysmorphism) and normal intelligence. "SRS is clinically similar to 3-M syndrome and has been associated with epigenetic alterations of the IGF2/H19 locus resulting in the loss of IGF2 expression." (PMID 24711643, 2014). "3-M syndrome is associated with a gene expression profile of reduced IGF2 expression and increased H19 expression similar to that found in Silver–Russell syndrome." (PMID 24148222, 2013).
acromegaly (2 papers, 2023 to 2025). Acromegaly is an acquired disorder related to excessive production of growth hormone (GH) and characterized by progressive somatic disfigurement (mainly involving the face and extremities) and systemic manifestations. "For the first time, an association between cholelithiasis and H19 expression in acromegaly was revealed." (PMID 37189829, 2023). "We found an association between H19 and cholelithiasis in acromegaly patients." (PMID 37189829, 2023). "We investigated whether whole blood H19 RNA expression is associated with the diagnosis of acromegaly." (PMID 37189829, 2023). "We analysed the coincidence of acromegaly comorbidities with H19 RNA expression." (PMID 37189829, 2023). "According to the obtained results, the whole blood expression of H19 is not a relevant diagnostic or monitoring marker for acromegaly." (PMID 37189829, 2023). "Patients with active acromegaly (de novo or uncontrolled during SSA therapy) did not vary in H19 expression from radically operated or controlled subjects." (PMID 37189829, 2023). "In the results, we did not observe a statistically significant difference in H19 RNA expression between acromegaly patients and the controls." (PMID 37189829, 2023). "No variations in H19 expression were observed between patients with pituitary insufficiency among all participants nor between acromegaly and control groups." (PMID 37189829, 2023). "To conclude, H19 RNA expression is not a relevant marker for diagnosis and monitoring of acromegaly patients." (PMID 37189829, 2023).
adenoma (2 papers, 2015 to 2023). A neoplasm arising from the epithelium. "Increased DNA methylation levels of the H19 ICR were observed for four adenomas (samples 17, 19, 30, and 31)." (PMID 26400872, 2015). "However, in our study, we did not observe any differences in H19 expression between patients with invasive and non-invasive adenomas." (PMID 37189829, 2023).